BCL2 (BCL2 apoptosis regulator)
Diseases named in the same sentence as BCL2 in open-access papers (continued):
Sharing a sentence is not in itself a finding about the gene and the disease.
ischemia (106 papers, 2008 to 2026). A hypoperfusion of the BLOOD through an organ or tissue caused by a PATHOLOGIC CONSTRICTION or obstruction of its BLOOD VESSELS, or an absence of BLOOD CIRCULATION. "Bcl-2, an anti-apoptotic protein, significantly decreased in the groups with ischemia and I+R, reflecting increased susceptibility to apoptosis." (PMID 40001595, 2025). "The C5.0 decision tree indicates that cardiac grafts from the ischemia+AAT (1h and 5h after ischemia) are associated with increased expressions of myocardial Flt1, Cflar, and Bcl2, hence supporting the protective effects of AAT." (PMID 37426668, 2023). "Infarct volume, sensorimotor function, neurological deficits, and cellular expressions of brain-derived neurotrophic factor (BDNF), B-cell lymphoma 2 (Bcl-2), Bcl-2-associated X protein (Bax), and caspase 3 were evaluated 48 h after the induction of ischemia." (PMID 36750711, 2023). "The current results showed that overexpression of miR-98 reversed the reduction in Bcl-2 expression caused by acute ischemia, suggesting that Bcl-2 is involved in miR-98-induced cardioprotection." (PMID 28784995, 2017). "Reversible blockade of electron transport during ischemia preserves the bcl-2 content accompanied by decrease in susceptibility to MPTP opening following ischemia." (PMID 25756500, 2015). "There are reports that activation of NF-κB induces expression of genes encoding anti-apoptotic proteins such as Bcl2 and protects neurons against oxidative stresses or ischemia-induced neurodegeneration." (PMID 23880112, 2013). "Decreased bcl-2 content is associated with increased MPTP opening in ischemia-damaged SSM." (PMID 25756500, 2015). "If a decreased bcl-2 content or functional inhibition contributes a key role in the reperfusion-induced susceptibility to MPTP opening compared to ischemia alone, then overexpression of bcl-2 should inhibit the MPTP opening in cardiac mitochondria following ischemia-reperfusion." (PMID 25756500, 2015). "This study showed that in the depression with myocardial ischemia/reperfusion group, Bcl-2 expression increased significantly with an increase of Bax expression, his also might be caused by ischemia/reperfusion stimulating Bax expression and decreasing the formation of heter Bcl-2/Bax." (PMID 25471226, 2014). "It was also reported that berberine has antiapoptotic effects against ischemia by reducing caspase-3 and increasing the Bcl-2/BAX ratio." (PMID 40235540, 2025). "At the same time, the qPCR analysis demonstrated that Bcl-2 expression was significantly decreased in both the ischemia and IR groups compared to the control group, whereas caspase-3 expression was increased." (PMID 40235540, 2025). "In a study using a male mouse model, the relationship between stress and stroke was explored through analysis of ischemia-induced Bcl-2 expression." (PMID 41567533, 2025). "Bcl-2 immunoreactivity level was significantly decreased in the ischemia group compared to the control group." (PMID 40235540, 2025). "In our study, immunohistochemical analyses showed that Bcl-2 positivity decreased in spermatogenic cells in the ischemia and IR groups in testicular tissue and increased due to the B. vulgaris extract dose increase." (PMID 40235540, 2025). "Using cell-based assays, we show that PDGF-D stimulation improves the survival of human brain pericytes exposed to ischemia and reperfusion-like conditions by increasing BCL2 expression." (PMID 38769116, 2024). "Gal‐3 knockdown attenuates cardiac ischemia–reperfusion injury by interacting with Bcl‐2, modulating mitochondrial function, and inhibiting inflammation response in cardiomyocytes, possibly through regulation of the JNK pathway." (PMID 39230472, 2024).
ischemia (continued). "The process of ischemia itself caused an increase in the expression of TLR4, NF-κB and Bax and a decrease in Bcl-2 levels, thereby contributing to increased apoptosis in the rat heart." (PMID 39338354, 2024). "The drug’s administration contributed to an increase in Bcl-2 protein expression and a decrease in Bax protein expression in cardiac tissue compared to the group of rats after an episode of ischemia alone." (PMID 39338354, 2024). "Studies have demonstrated that cardiac-specific overexpression of inhibitor of apoptosis (BCL-2) significantly reduces infarction size after ischemia-reperfusion injury (I/R injury)." (PMID 39184397, 2024). "Although a large number of genes are involved in regulating apoptotic cell death, the antiapoptotic Bcl-2 and proapoptotic Bax proteins play major roles in the induction of myocardial apoptosis following ischemia and reperfusion." (PMID 36830962, 2023). "In contrast to the control and vehicle groups, pretreatment with NHWD-870 prior to the induction of ischemia significantly increased the level of Bcl-2 in the pretreatment group." (PMID 37675155, 2023). "In ischemic rats pre-treated with βCAR-10 and βCAR-20, the Bax/Bcl-2 ratio was significantly decreased compared to the ischemia group." (PMID 36552554, 2022). "Bcl-2 is an anti-apoptotic protein which expression is important for retinal survival after ischemia." (PMID 35281489, 2022). "The present study demonstrates that IPC has a neuroprotective effect on ischemia by modulating the Bax/Bcl2 mRNA ratio." (PMID 34131232, 2021). "Expression of Bcl-2, an anti-apoptotic regulator, is induced in the brain by ischemia consistent with the potential role of this protein as part of endogenous neuro-protective mechanism." (PMID 31907023, 2020). "In this study, we found that compared with vehicle treatment, paeonol significantly increased the ratio of Bcl-2 to Bax in the myocardium after ischemia for 1 h and reperfusion for 3 h." (PMID 33551799, 2020). "Studies have shown that Bcl2 is a apoptosis-related factor and that Bcl2 can reduce brain damage induced by ischemia/reperfusion injury and enhance the survival of hippocampal neurons after ischemic damage." (PMID 32576868, 2020). "miR-155 inhibition prevented the downregulation of H2O2 induced BCL-2 in cardiomyocytes and was protective against ischemia-induced apoptosis in vivo." (PMID 33391256, 2020). "Following ischemia, the number of neurons expressing the anti-apoptotic protein, Bcl-2, significantly decreased by 12 ± 5 and 19 ± 8% in cells exposed to ischemia alone or ischemia in the presence of afobazole, respectively." (PMID 31156357, 2019). "Although there was a decrease in Bcl-2 protein, elevation in the pro-apoptotic protein Bax was detected after ischemia." (PMID 31235613, 2019). "The relationship between afobazole and the expression of the anti-apoptotic gene, Bcl-2, was examined using immunocytochemical analysis of microglia following ischemia." (PMID 31156357, 2019). "The failure of σ receptors to affect Bax, caspase-3, and Bcl-2 levels in neurons following ischemia suggests that different pathways must be involved in σ receptor protection of neurons and microglia, respectively." (PMID 31156357, 2019). "In the nesfatin-1 treatment group, the percentage of Bcl-2-positive cells increased (37.1%±3.31) compared to the ischemia group (P<0.05)." (PMID 32284834, 2019). "Bcl-2 and Bax play important pathophysiological roles in the protection and acceleration, respectively, of myocyte apoptosis after ischemia and/or reperfusion." (PMID 29439657, 2018).
ischemia (continued). "RBP-J-mediated Notch signaling also protects against ischemia-induced myocardial injury through the modulation of the expression of bax and bcl-2, which activates caspase 3 expression and leads to cardiomyocyte apoptosis." (PMID 30065940, 2018). "Up-regulation of anti-apoptotic members of the Bcl-2 family, including Bcl-2 and Bcl-xL, has been reported to be mediated by p38 in carbon monoxide-protected ischemia/reperfusion injury of the lung, and in HaCaT keratinocytes exposed to ultraviolet A (UVA)." (PMID 28537893, 2017). "Especially in recent years, the question of how to promote Bcl-2 protein expression in dysfunctional mitochondria has become a major issue in the treatment of ischemia-injured vascular cells." (PMID 27885275, 2016). "Since Akt and GSK-3β regulate the myocardial apoptotic pathway, we evaluated Bax and Bcl-2 expression levels after ischemia/reperfusion." (PMID 27077846, 2016). "More importantly, we demonstrated that miR-1 and miR-195 expression was decreased in the RIPerc group but their common target gene, Bcl-2, was increased in atrial myocardium during ischemia." (PMID 26738985, 2016). "The present study found that ischemia-damaged mitochondria with electron transport chain induced depletion of bcl-2 can mediate cardiomyocyte cell death during reperfusion by reinforcing mechanisms and timing." (PMID 25756500, 2015). "We attempted to employ an analytical approach to assess the interaction of bcl-2 with sensitizer and activator peptides in response to ischemia and/or reperfusion using co-immunoprecipitation, but this approach proved to be experimentally challenging." (PMID 25756500, 2015). "The decreased bcl-2 content after ischemia favors sequestration of the residual bcl-2 in ischemia-damaged SSM by these activators and sensitizers leading to sensitization to MPTP opening during early reperfusion." (PMID 25756500, 2015). "This is based on studies using various approaches (including caspase-3 activity, Bax activation, cytochrome c release and changes in the Bcl-2/Bax ratio) that have demonstrated that apoptosis is a consequence of ischemia." (PMID 25667634, 2015). "It was reported that the level of the key anti-apoptotic protein, Bcl-2, was decreased after myocardial ischaemia-reperfusion (I/R) 5, and overexpression of pro-survival Bcl-2 family proteins protected against myocardial I/R injury and attenuated apoptosis." (PMID 25898913, 2015). "When the level of Bcl-2 (26–29 kDa) in the sham group was set at 1.00, the level of Bcl-2 was 0.49±0.05 in the ischemia group, 0.66±0.03 in the ischemia and 50,000 units ulinastatin group, and 0.98±0.01 in the ischemia and 100,000 units ulinastatin group." (PMID 25891426, 2015). "In the present study, titration of HA14–1 further sensitizes to mitochondrial MPTP opening in ischemia-damaged SSM, suggesting that further functional bcl-2 inhibition increases MPTP opening in ischemia-damaged mitochondria." (PMID 25756500, 2015). "When the ratio of Bax to Bcl-2 in the sham group was set at 1.00, the ratio of Bax to Bcl-2 was 8.46±1.50 in the ischemia group, 4.85±0.83 in the ischemia and 50,000 units ulinastatin group, and 2.34±0.57 in the ischemia and 100,000 units ulinastatin group." (PMID 25891426, 2015). "In the G1 and E2 groups, in which the H9C2 cells had been subjected to 20 min of ischemia followed by 120 min of reperfusion, the Bcl-2 mRNA expression, as measured by qPCR, was higher than that in the control group." (PMID 25936661, 2015). "The decreased bcl-2 content during ischemia favors the unopposed action of pro-death activator peptides to access and activate bax and bak leading to increased permeability of the outer membrane." (PMID 25756500, 2015). "Hippocampal GFAP was also significantly elevated, while Bcl-2 and sirtuin 1 decreased significantly in response to ischemia." (PMID 26594596, 2015). "The results also showed the BCL-2 gene expression was declined in ischemia group as campared to PNT drug group." (PMID 24734070, 2014).
ischemia (continued). "This study highlights a previously unrecognised beneficial action of IVIg on cerebral endothelial cells exposed to ischemia, in that cell death is inhibited and levels of Bcl-2 and Bcl-XL are preserved." (PMID 24991401, 2014). "Overexpression of bcl-2 in transgenic mice protected neurons from naturally occurring cell death and experimental ischemia." (PMID 24250658, 2013). "In the present study, bcl-2 promoted the transcription of mRNA in the drug group, but prevented the transcription of mRNA in the ischemia group." (PMID 24250655, 2013). "The results also showed the bcl-2 gene expression declined in ischemia group as compared to the drug group." (PMID 24250655, 2013). "Pentoxifylline effects on bcl-2 gene expression changes in hippocampus after ischemia-reperfusion were compared with the ischemia group." (PMID 24250655, 2013). "In this study, we have designed and optimized quantitative real-time PCR assay based on SYBR Green I chemistry to determine the effect of PTX on bcl-2 gene expression changes in hippocampus after ischemia-reperfusion injury in rat." (PMID 24250655, 2013). "The supportive role of A2A receptors in the reduction of neural defects due to ischemia is shown by a decrease in apoptosis after the use of A2A receptor agonists that are related to the changes of expression in Bax and Bcl-2 genes." (PMID 23508639, 2012). "Reperfusion injury of skeletal or cardiac muscle was markedly reduced by intraperitoneal or subcutaneous injection of recombinant human (rh)BCL2 protein or rhBCL2-related protein A1 (BCL2A1) (50 ng/g) given prior to ischemia or at the time of reperfusion." (PMID 20161703, 2010). "On the other hand, recent evidence has shown that minocycline in the periphery affords protective effects on kidney cells against ischemia via the apoptotic Bcl-2/cytochrome c pathway." (PMID 19807907, 2009). "Mechanistically, the protective effect of HSYA in alleviating myocardial injury after ischemia may be associated with NLRP3 inflammasome, Bcl-2, Bax, caspase-3, eNOS proteins, and TLR/NF-κB, Nrf2/HO-1, JAK/STAT, PI3K/Akt, AMPK/mTOR, VEGFA pathways." (PMID 40271057, 2025). "The Bcl-2 immunoreactivity level was significantly higher and caspase-3 immunoreactivity level was significantly lower in the B. vulgaris extract-treated groups compared to the ischemia and IR groups." (PMID 40235540, 2025). "Similarly, the apoptosis gene marker BAX exhibited a significant upregulation in experimental subgroup 2 compared to both the control and the ischemia group, while the anti-apoptotic BCL2 gene expression remained unchanged." (PMID 40009267, 2025). "However, the antiapoptotic gene Bcl-2 expression was significantly decreased in both the ischemia and IR groups compared to the control group." (PMID 40235540, 2025). "Bcl-2 levels decreased in the ischemia group but increased with EA and BER (p < 0.05)." (PMID 40142262, 2025). "Additionally, in vitro experiments also demonstrated abundant WWP1 protein expression, accompanied by low anti-apoptotic protein Bcl2 in neonatal rat cardiac myocytes (NRCMs) exposed to simulated ischemia by deprivation of glucose and oxygen." (PMID 36593958, 2023). "Moreover, reducing miR-208 expression can upregulate the target gene p21 to promote ROS production, upregulate Bax expression, downregulate Bcl-2 expression, and aggravate ischemia-reperfusion-induced myocardial apoptosis." (PMID 34504644, 2021). "Furthermore, it is also reported that the increases in the proportion of Bcl-2 to BAX can prevent myocardial apoptosis progress induced by ischemia and reperfusion." (PMID 33013403, 2020).
ischemia (continued). "In addition to inhibiting increases in Bax and activated caspase-3 in microglia, afobazole produced an increase of Bcl-2 expression in microglia that was more pronounced following ischemia." (PMID 31156357, 2019). "Additionally, olive oil treatment of hippocampus CA1 neurons following ischemia in mice also reduced apoptosis by decreasing Bax and increasing Bcl-2 expression." (PMID 30004416, 2018). "NO negative control CREB activation, we thus investigated whether Tat-HA-NR2B9c affects CREB activation and expression of Bcl-2 after ischemia." (PMID 29018405, 2017). "Thus, these miRNAs constitute potential drug targets for vascular protection by specifically regulating Bcl-2 expression and maintaining mitochondrial homeostasis against ischemia insult." (PMID 27885275, 2016). "The data further supports that the neuroprotective effect of EA pretreatment against ischemia-induced apoptosis might be at least partly mediated by regulating Bax and Bcl-2 expression through GluR2 up-regulation." (PMID 25830356, 2015). "15d-PGJ2 can also restrain the autophagy of neurons in the ischemia lesion by upregulating Bcl-2." (PMID 26844229, 2015). "Interestingly, cardiac specific overexpression of Bcl-2 has been shown to reduce the rate of fall in ATP during ischemia and to reduce ischemic acidification." (PMID 25559887, 2015). "Conversely, we observed decreased levels of p-Akt Ser473, p-mTOR Ser2448, and mTOR activity concomitant with the decline of tauopathy and neuronal loss at 30 days post-ischemia in the absence of changes in Bcl-2 protein levels, suggesting apoptotic regulation." (PMID 26042033, 2015). "The bcl-2 content is decreased in cardiac mitochondria following ischemia." (PMID 25756500, 2015). "In addition, bcl-2 mRNA expression significantly declined in the ischemia group as compared to drug group." (PMID 24250655, 2013). "CMS decreased Bcl-2 gene expression in the ischemia rats, which was reversed by DAPT treatment." (PMID 22912748, 2012). "Recent studies indicate that CREB may be a key element in the acquisition of ischemic tolerance in the brain, and that IPC induces CREB activation and Bcl-2 expression in a neonatal ischemia model." (PMID 21633713, 2011). "Similarly, Neuroprotectin D1, derivative of docosahexaenoic acid (DHA), that promotes strong neuroprotection and neurotrophic activity following ischemia and reperfusion, also up-regulates Bcl-2 and Bcl-xL." (PMID 19775433, 2009). "Accumulating evidence has indicated that an increase in the Bcl-2 (Bcl-xL)/Bax ratio inhibits Bax translocation to the mitochondria and protects neurons against apoptotic insults, whereas a shift in the balance toward an excess of Bax elicits ischemia-induced neuronal apoptosis." (PMID 27187745, 2016). "Therefore, we hypothesized that RIPerc inhibits the increase in miR-1 and miR-195 expression in atrial myocardium during ischemia, resulting in increased Bcl-2 expression, which attenuates apoptosis in myocardium." (PMID 26738985, 2016). "The findings of this study reveal a beneficial effect by IVIg on ischemia-induced leukocyte recruitment as well as on endothelial permeability (mediated by tight-junction proteins claudin 5 and occludin), as well as an anti-apoptotic effect on endothelial cells mediated by Bcl-2 and Bcl-XL." (PMID 24991401, 2014). "Therefore, this increased Bcl-2/Bax ratio might have contributed to decreased retinal neuron degeneration following ischemia." (PMID 24455299, 2013). "Our previous study demonstrated that AS-IV prevented ischemia-induced AKI in rats by inhibiting oxidative stress and apoptosis, and the mechanisms of renoprotection by AS-IV were associated with restoring the balance of Bax and Bcl-2 expression and inhibiting caspase-3 and p38 MAPK activation." (PMID 23853656, 2013). "Following localized and global ischemia and TBI, damaged neurons showed decreased Bcl-2 and elevated Bax immunoreactivity." (PMID 36959464, 2023).